TNF (tumor necrosis factor)
Diseases named in the same sentence as TNF in open-access papers (continued):
Sharing a sentence is not in itself a finding about the gene and the disease.
psoriasis (continued). "The macrophages have been proven to be the predominant source of TNF-α needed to initiate the inflammatory response for psoriasis-phenotype development." (PMID 31137673, 2019). "PSOLAR psoriasis patients with self-reported PsA in the TNF inhibitors, infliximab, adalimumab, etanercept, and MTX cohorts had numerically higher SI rates than the ustekinumab cohort, although not statistically significant." (PMID 31799498, 2019). "Previously, we have identified slanMo as inflammatory, iNOS- and/or TNF-α-expressing cells in tissues specimens of patients with psoriasis, lupus erythematosus, or graft-vs.-host disease." (PMID 30984181, 2019). "Apart from TNF-α, interleukin-6 (IL-6), interleukin-12 (IL-12) and interleukin-23 (IL-23) are also involved in the pathogenesis and clinical manifestations of psoriasis." (PMID 31291937, 2019). "Though TNF-α, IL-17, and IL-23 play a key role in the general pathophysiology of psoriasis, especially plaque psoriasis, there are additional relevant pathways in other variants of psoriasis." (PMID 31590274, 2019). "Elegant studies, in either T cell- or skin-dependent models of psoriasis, established the critical role of macrophages as a source of TNFα, substantiated by anti-TNFα rescue studies or depletion of macrophages." (PMID 31357710, 2019). "Patients with psoriasis and HS have elevated levels of tumor necrosis factor (TNF) and interleukin-17 (IL-17) in lesional and non lesional tissues, which has been the justification for selective targeting of these inflammatory pathways." (PMID 33456757, 2019). "On this topic, further anti-TNF agents, such as infliximab and adalimumab, which are already used for the treatment of psoriasis, were evaluated in NAFLD patients." (PMID 31540048, 2019). "Compared to TNF-α inhibitors, the newer biologics for psoriasis such as anti-IL-12/23 and anti-IL-17A agents are generally considered with a lower risk of active TB or LTBI reactivation." (PMID 31881026, 2019). "ERK phosphorylation can also activate Th17 cells and then promote the secretion of inflammatory cytokines TNF-α, IL-6, and IL-17A, which positively correlate with psoriasis." (PMID 31824416, 2019). "Said changes in DNA methylation reverted to baseline under anti-TNF-α treatment, indicating that CpG methylation in psoriasis is dynamic." (PMID 30909615, 2019). "Tumor necrosis factor-α (TNF-α) plays a central role in the complex cytokine network of psoriasis, as demonstrated by the clinical efficacy of monoclonal antibody therapy (anti-TNF-α) in psoriatic patients (i.e., with infliximab)." (PMID 31100904, 2019). "For instance, several pro‐inflammatory cytokines and arachidonic acid metabolic pathways described to be critical in psoriasis, such as IL‐23, IL‐1α, TNF‐α, TSLP, or PTGS2, were up‐regulated." (PMID 31556482, 2019). "For example, patents treated with TNF blocking agents sometimes develop paradoxical psoriasis and this is resulted from an overproduction of IFNα from pDCs upon TNF inhibition." (PMID 31293591, 2019). "Examples include etanercept (Enbrel®), a TNF-α antagonist and secukinumab, an antibody anti-IL-17A antagonist for psoriasis treatment." (PMID 31540162, 2019). "Anti-tumor necrosis factor alpha (TNF- α) therapy has made a significant impact on treating psoriasis." (PMID 30953507, 2019). "TNF-α inhibitors are the first generation of biologic medications for psoriasis, and they have been successfully used to treat moderate-to-severe psoriasis for over a decade." (PMID 31590274, 2019). "Both naringin and sericin alone significantly decreased the expression of mRNA and the production of TNF-α, IL-6, IL-23, and IL-12p40 by hPBMCs from psoriasis patients, with similar potency of activity." (PMID 31291937, 2019). "TNFα-neutralizing Abs have been widely used to treat several autoimmune and immune-mediated disorders, such as RA, psoriasis, and Crohn disease." (PMID 31194726, 2019).
psoriasis (continued). "Recent studies focused extensively on the role Th17 cells in the pathogenesis of psoriasis, in part due to their high concentration in psoriatic lesions and significant reduction following anti-TNF-α treatment." (PMID 31590274, 2019). "The mRNA expression levels of TNF-α, IL-6, IL-12p40 and IL-23 genes in hPBMCs obtained from psoriasis patients were significantly higher than that from healthy control (30.22, 7.5, 6.8 and 22.4 fold, respectively, P < 0.001)." (PMID 31291937, 2019). "Psoriasis treatments are based on immunosuppression/immunomodulation (methotrexate, anti-TNF-α, and anti-IL-17) to reduce or neutralize the production of cytokines." (PMID 31789260, 2019). "TNF-α inhibitors are still the standard used to evaluate drug efficacy in psoriasis clinical research." (PMID 30909615, 2019). "Despite these agents being designed to block TNF- α activity, their mechanism of action in the remission of psoriasis is still not fully understood at the molecular level." (PMID 30953507, 2019). "In the early stages of psoriatic plaques, dermal involvement is dominant, including immune-cell infiltration and production of TNFα as one of the main executor cytokines in psoriasis." (PMID 31836722, 2019). "TNF-α is a pleiotropic, pro-inflammatory cytokine involved in both the innate and adaptive arms of the immune response in psoriasis." (PMID 31590274, 2019). "The experimental results of this study show that the EPS/CPT emulsion can effectively reduce the levels of the inflammatory factors IL6 and TNF in peripheral blood to alleviate the symptoms of psoriasis." (PMID 31861934, 2019). "slanMo have been found at increased frequencies in psoriasis skin lesions and these numbers rapidly normalized with clinically effective anti-TNF therapy." (PMID 31191513, 2019). "In psoriasis patients treated with the JAK1/2 inhibitor baricitinib or the TNFα antagonist etanercept, IL-19 levels were also highly correlated with PASI scores, and decreases correlated with PASI improvement." (PMID 30914699, 2019). "Proinflammatory cytokines, such as IL-33, osteopontin (OPN), IL-17, and TNF-α, are involved in both psoriasis and PsA pathogenesis as well as in bone homeostasis." (PMID 31659208, 2019). "In conclusion, TNF-α, IL-6 and IL-1β are increased in psoriasis and correlate with PASI scores and obesity, leading to worsening of psoriatic lesions." (PMID 31521168, 2019). "TNF-α increases the upregulation of adhesion molecules and secondary mediators, both of which are related to the development of psoriasis." (PMID 31137673, 2019). "TNF-α-producing slanMo were identified in psoriasis, lupus skin lesions, glomerular capillaries of lupus nephritis, and tumor draining lymph nodes." (PMID 31191513, 2019). "New biological drugs targeting the TNF/IL-23/IL-17 pathways have shown to be safe and efficacious in recent psoriasis clinical trials." (PMID 31293591, 2019). "Paradoxical induction of psoriasis in patients treated with TNFα inhibitors has been attributed to shifts within the balance of TNFα and type I interferons (IFNα) with impact on plasmacytoid dendritic cells." (PMID 31402919, 2019). "A selective AHR agonist, tapinarof is currently being studied because this medicinal agent improves both psoriasis and AD in which different pathomechanisms operate (the TNF-α/IL-23/IL-17 axis in psoriasis and IL-4/IL-13 signaling in AD)." (PMID 31683543, 2019). "IR is strongly influenced by the activity of pro-inflammatory adipocytokines, as TNF-α, IL-6, and leptin, inducing a state of persistent low-grade inflammation that underlies the physiopathology of both NAFLD and psoriasis." (PMID 31540048, 2019). "The natural history of psoriasis has been modified in the last years by new biologic agents that have allowed specific targeting of key cytokines such as TNF alpha, IL-12, IL-23 and IL-17." (PMID 31448100, 2019).
psoriasis (continued). "The production of IL-12 by CD4+ Th1 and CD8+ cytotoxic T cells along with IFN-γ and TNF-α in a pattern known as the type I cytokine pattern contributes to pathogenesis of psoriasis." (PMID 31130981, 2019). "TNF-α inhibitors etanercept, adalimumab, and infliximab are approved for moderate-to-severe psoriasis management." (PMID 31137673, 2019). "The expressions of crucial inflammatory mediators (including IL-1β, IL-2, IL-6, IL-10, IL-17, IL-22, IL-23, IFN-γ, TNF-α) in skin tissues were measured by ELISA due to the import role of inflammatory cytokines in psoriasis." (PMID 31181689, 2019). "Previous studies had also showed VEGF down-regulation in psoriatic skin lesions and in cutaneous mesenchymal stem cells from psoriasis patients responding to the anti-TNF therapy." (PMID 30953507, 2019). "Selectively targeting specific cytokines (TNF-α, IL-17 and IL-12/23) and/or intracellular signaling pathways effectively prevent disease progression by ameliorating cutaneous inflammation of psoriasis and inhibiting osteoclastogenesis." (PMID 30658492, 2019). "This gene codes for the transcription factor involved in regulating the proliferation and differentiation of keratinocytes and was found to be overexpressed in psoriasis which subsequently leads to overproduction of TNF-α and the resultant inflammation." (PMID 31130981, 2019). "Activated macrophages then produce inflammatory cytokines such as IL (interleukin)-6 and TNF (tumor necrosis factor) which are known to exacerbate the symptoms of psoriasis as well." (PMID 31316526, 2019). "In nail psoriasis and psoriatic arthritis (PsA), an increased expression of TNF-α, NFκB, IL-6, and IL-8 in psoriasis-affected nails is consistent with the inflammatory markers found on lesional psoriatic skin." (PMID 30909615, 2019). "TNF-α, which plays a crucial role in psoriasis by increasing keratinocyte proliferation and angiogenesis, was found to be increased in human and animal models of NAFLD, contributing to IR and uncontrolled lipolysis." (PMID 31540048, 2019). "In a related approach, a dual inhibitor targeting simultaneously TNF and IL-17 has been tested and shown to be effective in reducing pathology in RA and psoriasis murine models." (PMID 31877657, 2019). "CD83 is a marker for mature/activated dendritic cells, which are a major source of TNF in psoriasis lesions and provide signals for direct intralesional T cell activation." (PMID 30953507, 2019). "With respect to diabetes, higher rates of psoriasis (~1.76-fold), especially of severe psoriasis (~2.1-fold), have been reported, and elevated levels of TNF seem mainly to be responsible via JNK activation and subsequent IRS-1 phosphorylation." (PMID 32010143, 2019). "In the group of psoriasis patients, 10 patients were on anti-TNF and 14 patients on methotrexate treatment, while 8 individuals were not treated." (PMID 31101850, 2019). "Here, we elucidate the cellular and molecular “scar” and its imprints left after clinical resolution of psoriasis treated with anti-TNFα, anti-IL-17, or anti-IL-23 antibodies or phototherapy." (PMID 31673756, 2019). "TNF alpha inhibitors are the oldest, and therefore most studied, biologic drugs that have been introduced in the therapy of psoriasis." (PMID 31448100, 2019). "In contrast, TNF blockade leads to an ongoing type-I IFN mediated acute inflammation in paradoxical psoriasis." (PMID 30555460, 2018). "Increased secretion of TNF-α was observed in rheumatoid arthritis, ankylosing spondylitis, psoriasis, and inflammatory bowel disease." (PMID 29487864, 2018). "Once the cutaneous inflammation is stimulated by the antigen, macrophages, keratinocytes, Th1 cells, T17 cells, Th22 cells and BDCA-1−inflammatory DCs will produce TNF-α, which plays an important role in the inflammatory process in psoriasis." (PMID 29416693, 2018).
psoriasis (continued). "The cytokines most convincingly demonstrated to mediate psoriasis plaque formation are those for which inhibition has been effective in patients, such as IL-23, TNF, and IL-17A." (PMID 29434599, 2018). "At the skin lesions of psoriasis, the accumulation of cytokines, such as IL-2 and TNF-alpha, will promote the development of psoriasis." (PMID 29588654, 2018). "HBVr as a consequence of anti-TNF agents has been mainly reported in patients suffering from diseases different from psoriasis, such as inflammatory bowel disease and rheumatic disorders." (PMID 29546055, 2018). "Despite this evidence, IL-17C was shown to be upregulated in paradoxical psoriasis upon anti-TNF therapy in patients presenting inflammatory bowel disease (IBD), in a mechanisms depended on IL-36γ." (PMID 30127781, 2018). "Biologics targeting cell-to-cell signaling through TNF or the IL-23/IL-17 pathway have revolutionized the clinical management of severe psoriasis." (PMID 29520279, 2018). "Among the upregulated genes, inflammatory mediators typical of psoriasis, including TNF-α, iNOS, IL-23p19, CCL19, ICAM-1, VCAM-1, and TRAIL were detected, concomitantly with an increased dermal infiltration of CD3+ T cells and CD11c+ DCs." (PMID 29316717, 2018). "In the context of paradoxical psoriasis, TNF blockade inhibits the induction of mature cDC and subsequent T-cell activation, while magnifying type I IFN-driven innate inflammation." (PMID 29295985, 2018). "Classical psoriasis is a T-cell mediated autoimmune disease driven by TNF, characterised by T-cells memory, and a relapsing disease course." (PMID 30555460, 2018). "Recently, researchers investigating the pathogenesis of psoriasis have postulated that the TNF/IL-23/type 17 inflammation axis is central to it." (PMID 29642409, 2018). "Th17 pathway was downregulated by NB-UVB in psoriatic epidermis, as suggested by significant decreases of IL-17A, TNF-α, and IL-6 mRNA in peripheral blood mononuclear cells (PBMCs) in psoriasis patients following NB-UVB treatment." (PMID 29067616, 2018). "Based on our current understanding of the immunopathogenesis of psoriasis, biologics have emerged that target TNF, IL-12/IL-23p40 subunit, IL-23p19 subunit, IL-17A, and the IL-17 receptor α chain (IL-17RA)." (PMID 29642409, 2018). "Psoriasis is a common skin disease pathogenically driven by TNF and IL-17A-induced epidermal hyperproliferation and inflammatory responses." (PMID 30321197, 2018). "Another common side effect of TNF blockade is the development of inflammatory skin lesions, which resemble psoriasis and are observed in 2–5% of patients receiving anti-TNF therapy." (PMID 29295985, 2018). "Regarding clinical implications, only two Cochrane SRs provided high-quality evidence relating to use of anti-TNF agents for psoriasis in pediatric patients and use of combined therapy of steroids and vitamin D for scalp psoriasis." (PMID 30133547, 2018). "Inflammatory markers such as Th-1 cytokines (intracellular adhesion molecule-1, TNF-α) play a role not only in the pathogenesis of psoriasis, but also in the pathogenesis of metabolic syndrome, obesity, atherosclerosis, and myocardial infarction." (PMID 29662733, 2018). "Although TNF-α has been investigated in multiplestudies of psoriasis, the cytokines IL-12, IL-17, IL-19, IL-22, and IL-23 also playcentral roles." (PMID 29630472, 2018). "Curcumin has been reported to be an anti-psoriasis drug candidate by interrupting certain cytokines including TNF-α, IL-17, IL6 and INF-γ." (PMID 30301277, 2018). "Cytokines play a central role in the psoriasis disease process, particularly IL-17A and TNF-α, as highlighted by the efficacy of recently-developed biologic drugs targeting these molecules in psoriasis." (PMID 30321197, 2018). "In the pathogenesis of psoriasis, a prominent role for TNF has been described and this is illustrated by the success of the TNF inhibitors in this disease." (PMID 29751683, 2018).
psoriasis (continued). "In a recent publication, a subset of myeloid cells expressing CD5 promoting induction of IL-22, IFNγ, TNF, and granzyme B in mixed lymphocyte reaction assays was enriched in psoriasis epidermis." (PMID 29520279, 2018). "Because the pro-inflammatory cytokine TNFα is critically involved in the early phase of psoriasis, we next examined the effect of TNFα activation on the response to DHA ligands." (PMID 29401702, 2018). "Under this principle, we investigated the influences of hyperlipidemia in imiquimod (IMQ)-induced psoriasis-like B6.129S2-Apoetm1Unc/J mice and oxidized low-density lipoprotein (oxLDL) in tumor necrosis factor (TNF)-α-stimulated Hacat cells." (PMID 30177636, 2018). "Effects of TNF-α inhibition in psoriasis and PsA are complex, because therapeutic benefits likely result from indirect adaptive immune effects on the IL-23/IL-17A axis." (PMID 30109481, 2018). "The immunological events leading to the described epidermal changes are well understood and various “biologics” against different inflammatory cytokines such as TNF-α, IL-17A, or IL-12/IL-23 show promising results in the therapy of psoriasis." (PMID 30555471, 2018). "T helper (Th) cells Th1 and Th17 are predominantly responsible for the inflammatory immune response in psoriasis by inducing a cascade of inflammatory cytokines, notably tumor necrosis factor (TNF)." (PMID 29751529, 2018). "Previous studies have demonstrated elevated levels of TNF-α in the serum and skin of psoriasis patients." (PMID 30054515, 2018). "Psoriasis lesions contain elevated levels of TNF-α and IL-17A, cytokines recognized as important mediators of cutaneous inflammation." (PMID 30321197, 2018). "Recapitulating psoriasis skin, IL-17A+TNF-α treatment lead to increased expression of DEFB4, PI3, LCN2, S100A7, and IL36G mRNA over a 72 h time course without marked deterioration of tissue structure." (PMID 30321197, 2018). "Here we show that paradoxical psoriasis induced by anti-TNF is characterized by an exaggerated type I IFN response, which does not lead to T-cell autoimmunity." (PMID 29295985, 2018). "In the last decade, the management of psoriasis patients has been revolutionized with the introduction of biological therapies, such as tumor necrosis factor-alpha (TNF-α), interleukin (IL)-12/23, and IL-17 inhibitors." (PMID 30150978, 2018). "Their effector cytokines such as IL-17, IL-22, and TNF-α induce and maintain hallmarks of psoriasis such as keratinocyte proliferation, and disturbed differentiation, leading to epidermal acanthosis, hyperkeratosis, and parakeratosis." (PMID 30555471, 2018). "Psoriasis induces a Th1 inflammatory response at the affected site, leading to overproduction of TNF-α, IL-17, and IL-2317." (PMID 30038329, 2018). "Patients with psoriasis have higher levels of TNF-α and translation factors such as NF-κB in their skin lesions." (PMID 29679037, 2018). "Particularly, TNF inhibitors have become a benchmark for the treatment of numerous chronic inflammatory diseases such as psoriasis." (PMID 30555460, 2018). "We developed an ex vivo organotypic skin culture model using full-thickness normal human skin stimulated with IL-17A and TNF-α to mimic disease-related molecular changes in psoriasis skin." (PMID 30321197, 2018). "The current treatment options for psoriasis and psoriatic arthritis include TNF-α blockers and IL-12, IL-17, IL-23, T-cell and B-cell inhibitors." (PMID 29444128, 2018). "To model the cytokine-induced keratinocyte responses seen in psoriasis, we treated human skin organ cultures with TNF-α and IL-17A." (PMID 30321197, 2018). "It has been demonstrated that JNK is not active in healthy human epidermis, but its activity is increased in psoriasis; moreover, experimental data highlighted that TNF-α and UV light exert their pro-inflammatory effects in part via JNK activation." (PMID 29799444, 2018).